CRP (C-reactive protein)
Diseases named in the same sentence as CRP in open-access papers (continued):
Sharing a sentence is not in itself a finding about the gene and the disease.
depression (continued). "While a positive effect on depression outcomes was found in the main analyses, this did not persist when jointly estimating BMI and CRP effects for all depression outcomes, and additionally when using cis-MR." (PMID 37710313, 2023). "A separate network analysis showed that higher IL-6 and CRP more strongly coincided with increased somatic symptoms (i.e. aches, pains, sleep issues) v. other depression nodes in Dutch adults with and without elevated depression." (PMID 35924730, 2023). "Interestingly, at a high CRP level (>3 mg/L), the coexistence of HTG among the subjects with depression had a lower prevalence of RA (12.9%) than subjects with depression but not HTG (22.9%)." (PMID 38455932, 2023). "The hypothesis being tested in this trial is that promoting adherence to the MedDiet as an adjuvant to standard treatments for MDD can reduce symptoms of depression in patients with MDD and elevated inflammation biomarkers (IL-6 and CRP)." (PMID 37016319, 2023). "This study aims to understand if promoting adherence to the MedDiet, as an adjuvant strategy in the treatment of MDD, is effective to decrease symptoms of depression in patients diagnosed with MDD with high levels of inflammation biomarkers, namely elevation of CRP and/or IL-6 at baseline." (PMID 37016319, 2023). "In ReHo-altered brain regions, ReHo values were positively correlated with Hamilton Rating Scale for Depression (HAMD) scores, and the setting region of abnormal ReHo as seed points, voxel-wise FC between the SOG.L and PreCG.L was negatively correlated with CRP." (PMID 35992918, 2022). "In ReHo-altered brain regions, ReHo values were positively correlated with the Hamilton Rating Scale for Depression (HAMD) scores, and setting the region of abnormal ReHo as seed points, voxel-wise FC between the SOG.L and PreCG.L was negatively correlated with CRP." (PMID 35992918, 2022). "Perhaps this indicates that the subtype of depression to which people living with HIV are most susceptible is mediated by other inflammatory cytokines, but not CRP?" (PMID 35618889, 2022). "CRP was shown not to be related to depression when looking at MDD, but only increased in a subtype of depression with increased appetite." (PMID 35821205, 2022). "CRP and IL-6 at the first point of follow-up predicted cognitive symptoms of depression at follow-up, while baseline symptoms of depression did not predict inflammatory markers." (PMID 35163141, 2022). "Rodent models of depression have found similar increases in proinflammatory factors and proteins in the LHb, including tumor necrosis factor-a (TNF-a), C-reactive protein (CRP), and pro-inflammatory cytokines such as interleukin-1b (IL-1b), IL-6, and IL-10." (PMID 35359586, 2022). "When CRP was assessed as a mediator, it did not have a significant effect on depression (OR = 0.98; 95% CI : 0.92–1.04; p = 0.48)." (PMID 36057695, 2022). "GOLD groups-based assessment of TOPD severity did not demonstrate a significant correlation with anxiety, depression, CRP level, WBC count, or serum fibrinogen." (PMID 35371847, 2022). "However, in general, it is known that pro-inflammatory cytokines are increased in major depressive disorder (MDD), with the most remarkable increases in IL-6, TNF, and C-reactive protein (CRP)." (PMID 35884835, 2022). "Overall, these results do not support a role for CRP-indexed inflammation in the development of depression." (PMID 36057695, 2022). "The following were assessed immediately before and at the end of Ramadan: Serum CRP and stool calprotectin, partial Mayo score, Harvey Bradshaw index (HBI), Simple IBD questionnaire (SIBDQ), and Hamilton depression scale questionnaire." (PMID 35462542, 2022). "They indicated that individuals with current major depression, who suffered childhood maltreatment, were 1.48 times more likely to show high CRP levels than depressed individuals without childhood maltreatment." (PMID 36231913, 2022).
depression (continued). "In some cases, prospective data are weak and most meta-analyses of depression and CRP include studies in which the vast majority have not considered health confounds as done here." (PMID 35821205, 2022). "Similarly to manic episodes, serum levels of many inflammatory markers (CRP, TNF‐α, IL‐6, IL‐1β, sTNFR1, and CXCL10) are elevated during depressive episodes, and this alteration correlates with increased depression severity." (PMID 34590391, 2022). "In previous studies, elevated CRP levels have been found only in patients with atypical depression and not in patients with typical depression." (PMID 36551802, 2022). "Regarding the impact of RA on patient anxiety, studies have reported that c-reactive protein (CRP) levels may be correlated with anxiety and depression levels in RA patients." (PMID 35897734, 2022). "Various studies demonstrate that, e.g., schizophrenia, depression, suicidal ideation and post-traumatic stress disorder are characterized with increased levels of inflammatory markers, particularly IL-1β, IL-2R, IL-6, IL-17A, TNF-α and CRP." (PMID 35682824, 2022). "Although the IVW model did not demonstrate an effect of depression on CRP, MR-PRESSO and contamination mixture analysis did demonstrate this effect." (PMID 36057695, 2022). "Therefore, the aim of the current study is to investigate the potential effects of combination of saffron and chamomile on depression through PHQ 9 scale and related parameters such as tryptophan, BDNF, CRP." (PMID 36217471, 2022). "Stress and depression are related to high levels of proinflammatory biomarkers like interleukin (IL): IL-1β, IL-1α, IL-6, tumor necrosis factor-α (TNF-α), interferon-γ and C-reactive protein (CRP)." (PMID 36078738, 2022). "Patients with depression have increased pro-inflammatory cytokines in the blood, such as interleukin-6 (IL-6), interleukin-1β (IL-1β), tumor necrosis factor-α (TNF-α) and other acute-phase proteins and C-reactive protein (CRP)." (PMID 36357867, 2022). "We also identified depression loci conditional on TC, TG, T2D, LDL, HDL, CRP and vice versa." (PMID 35560157, 2022). "People with depression are characterized by increased levels of pro-inflammatory markers, such as interleukin (IL) IL-6, IL-1, tumor necrosis factor alpha (TNF-α) and C-reactive protein (CRP)." (PMID 36554751, 2022). "In patients with depression, the prevalence of high (>3 mg/L) C-reactive protein (CRP) levels, a biomarker for inflammation, has been shown to be 27% (95% CI, 21–34%), whereas, 58% (95% CI, 47–69%) of patients with depression had a mildly elevated CRP level (>1 mg/L)." (PMID 35370812, 2022). "For example, a study from German showed that both pro-inflammatory and anti-inflammatory markers, but not CRP were inversely correlated with the severity and symptoms of major depression." (PMID 36741577, 2022). "Conclusion: taVNS showed effects on CRP, IL-6, and depression levels; however, it did not affect other clinical symptoms." (PMID 36295080, 2022). "Overactivation of inflammatory responses and increased levels of inflammatory mediators like interleukin (IL)−1β, IL‐6, tumor necrosis factor alpha (TNF‐α), the acute phase reactant (CRP), and high mobility group box 1 (HMGB1) were seen in both patients and rodents with depressive disorder." (PMID 35089644, 2022). "Multiple meta analyses have indicated that patients diagnosed with clinical depression have higher levels of circulating proinflammatory markers, such as IL-1β, IL-6, TNFα, and C-reactive protein (CRP), than non-depressed individuals." (PMID 33435203, 2021). "These comments are hesitant at this stage because CM is associated with alterations in various important processes, and so it remains a highly relevant issue when diagnosing depression, even when CRP variations are absent." (PMID 34867491, 2021).
depression (continued). "The depressed cases (but not controls) were enriched for patients with CRP > 3 mg/L, potentially confounding depression- and inflammation-related effects on MRI markers." (PMID 34535766, 2021). "Re-analysing the data using this definition of depression did not change any of the main findings, nor did including the inflammatory marker data from the 62 participants that had a raised CRP (data not shown)." (PMID 33064180, 2021). "Moreover, a significant reduction in Hamilton Depression Rating Scale (HDRS), C-reactive protein (CRP), interleukin (IL)-10 and malondialdehyde (MDA) levels was found in patients with psychiatric disorders after probiotics supplementation." (PMID 33924064, 2021). "A negative correlation was found between CRP levels and the cortical thickness of the right medial prefrontal cortex (mPFC) in depression." (PMID 34975571, 2021). "However, interactions with environmental factors might lead to an increased risk for the emergence of depression as has been shown for MDD: adults diagnosed with MDD who have a history of early maltreatment exhibit higher CRP levels than those without such a history." (PMID 34764926, 2021). "In the first instance, the study aimed to assess whether serum CRP levels or PRS-CRP were increased in participants with a lifetime history of bipolar disorder, recurrent major depression, or a single episode of major depression." (PMID 33517931, 2021). "Elevated CRP levels have been found in some patients with depression without autoimmune, infectious, and malignant diseases." (PMID 34943627, 2021). "A prospective study showed that depression adults who experienced severe early life stress were 1.48 times more likely to have clinically high C-reactive protein (CRP) levels than those depression adults without early life stress." (PMID 34890365, 2021). "After adjusting for confounders, exclusive e-cigarette users had an OR for depression of 2.40 (95% CI: 1.10, 5.26), independent of serum CRP (unstratified)." (PMID 34639705, 2021). "As illustrated by the interaction plot, elevated values of CRP predicted new onset depression only in men and not in women." (PMID 33500534, 2021). "In comparison with healthy controls, patients with major depression have higher concentrations of inflammatory cytokines, including tumor necrosis factor (TNF)-α, interleukin (IL)-1β, IL-6, and C-reactive protein (CRP), while lower IL-10 concentration in blood." (PMID 34975477, 2021). "This pattern persisted for odds of depression among exclusive e-cigarette users with elevated CRP, suggesting a relationship between vaping and depression irrespective of current or previous history of tobacco product use." (PMID 34639705, 2021). "Of the 1002 participants with non-raised CRP concentrations, 116 had depression and 24 severe depression." (PMID 33064180, 2021). "By contrast, new onset of depression among men was related to living without a partner, lower socioeconomic status, higher inflammation markers (both CRP and WBC), and being physically inactive." (PMID 33500534, 2021). "As the stage of depression increased, the degree of current disease activity DAS28-CRP, patient overall disease-VAS was significantly increased, whereas age, disease duration and laboratory data including hemoglobin, albumin and CRP were unchanged." (PMID 34351967, 2021). "In women, lower age, a history of cancer, lower alcohol consumption, loneliness and baseline depression symptoms were predictive of depression, but not CRP." (PMID 33500534, 2021). "This negative result is discordant with several studies and meta-analyses showing higher levels of some immune factor in patients with depression compared to non-depressed controls, such as C-reactive protein (CRP), IL-6, and TNF-alpha." (PMID 34741019, 2021). "Finally, a number of studies have demonstrated scaling of CRP and/or IL6 with specific phenotypic dimensions of depression (such as anhedonia, psychomotor slowing, or anxiety)." (PMID 34535766, 2021).
depression (continued). "CRP levels were significantly elevated in treatment-resistant patients with depression but not so significantly in the treatment-responsive patients, compared with healthy individuals." (PMID 34943627, 2021). "In older adults, elevations in IL-6 and C-reactive protein (CRP) have been documented even prior to the onset of syndromal depression, suggesting that they are a “trait” rather than a “state” marker of depression." (PMID 34066585, 2021). "Similar findings have been reported for MS: CRP levels are elevated in patients with as compared to those without a relapse and correlate with depression severity." (PMID 34764926, 2021). "There was trend level evidence for differences between depressed and non-depressed participants’ CRP levels (χ2 = 5.56; p = 0.062), and increased levels of CRP with increasing severity of depression (χ2 = 4.84; p = 0.089)." (PMID 32339985, 2020). "Enhanced inflammation reported in the melancholic subtype in certain studies (e.g., elevated CRP, IL-6, TNF-α) could reflect the characteristics of the study cohort (e.g., patients with more severe symptoms of depression, inpatient)." (PMID 33255237, 2020). "In the same sample, we also find that blood levels of CRP, IL-3, IL-6, IL-12, IL-18, sIL-2R and TNF α are significantly elevated in patients with depression with medium-large effect sizes (range 0.54–1.97), and that these findings are robust to a range of potential confounds and moderators." (PMID 32113908, 2020). "The odds of moderate/severe depression were also increased for the persistently high CRP group, but this was not statistically significant; OR = 2.54 (95% CI, 0.90–7.16)." (PMID 31707310, 2020). "The results of the sensitivity analyses revealed that CRP remained a significant mediator in the relationship between PGS and subsequent somatic symptoms of depression after additionally controlling for cognitive-affective and somatic symptoms at wave 6 (β = 0.006, 95% CI, 0.002, 0.010)." (PMID 32398645, 2020). "Numerous studies conducted on patients meeting the criteria of the Diagnostic and Statistical Manual of Mental Disorders (DSM) for major depression have found significant increases in plasma or serum levels of CCL2, IFNγ, IL-1α, IL-1β, IL-2, IL-6, IL-8, IL-12 and TNF-α, together with CRP." (PMID 32545890, 2020). "Those with persistently elevated CRP also had increased odds of moderate/severe depression at 18, but this was not statistically significant." (PMID 31707310, 2020). "Third, accumulating evidence indicates that depression is related to a state of chronic low-grade inflammation, with significantly increased levels of interleukin (IL)-1, IL-6, tumor-necrosis factor (TNF)-alpha and C-reactive protein (CRP)." (PMID 32228541, 2020). "Furthermore, our findings of increased mean levels of CRP, IL-6, IL-12 and TNF α in depression replicate previous meta-analytical findings; the same can be said of no changes in levels of TGF β." (PMID 32113908, 2020). "Specifically, abnormally elevated granulocytes and monocytes numbers, enhanced C-reactive protein (CRP) and haptoglobin, chemokines, abnormalities of regulatory T-cells, and inflammatory cytokines have been documented in both patients with major depression and suicidal behaviors." (PMID 32244611, 2020). "CRP in particular has previously been found to correlate with depression severity after treatment and similar findings have been identified for MCP4 and TARC although the latter have scarcely been examined in depression intervention studies." (PMID 33276697, 2020). "Finally, these findings accord with the growing consensus that TNFα, IL-6 and CRP are among the important biomarkers with translational potential in mood disorders, suggesting that this may be true in the psychological as well as pharmacological treatment of depression." (PMID 33276697, 2020).
depression (continued). "In addition to our primary end point, development of proctitis, we evaluated secondary end points of quality of life (QOL), psychosocial status using Hospital Anxiety-Depression Scale (HAD), and also quantitative measurement of C - reactive protein (CRP)." (PMID 32404169, 2020). "In particular, tumor necrosis factor alpha (TNFα), interleukin-2 (IL-2), interleukin-6 (IL-6), interleukin-13 (IL-13), interleukin-18 (IL-18), C-reactive protein (CRP), chemokine-2 (CCL2), and chemokine-11 (CCL11) are elevated in depression based on multiple meta-analyses." (PMID 32351416, 2020). "The patients underwent clinical assessment based on Total Back Pain scores, Fatigue Severity Scale, Bath Ankylosing Spondylitis Disease Activity Index, (BASDAI), high-sensitivity C-reactive Protein (hsCRP), erythrocyte sedimentation rate (ESR), and Beck Depression Inventory (BDI)." (PMID 32500077, 2020). "Furthermore, the concentrations of interleukin-6, C-reactive protein, and tumor necrosis factor-α are increased in patients with CHD with co-morbid depression." (PMID 33584362, 2020). "The odds of moderate/severe depression were also increased for the persistently high CRP group, compared with low CRP group, but this was not statistically significant; adjusted OR 2.54 (95% CI, 0.90–7.16)." (PMID 31707310, 2020). "In addition, age, sex, widowhood, higher initial stroke severity, 3-month functional disability and serum levels of Hs-CRP and HCY were significant indicators for depression, different from others factors." (PMID 32040942, 2020). "In order to gain further insight into the relationship between inflammation and depression, we present another longitudinal study based on the ALSPAC cohort that examines the relationships between IL-6 and CRP at age 9 years and 19 specific symptoms of depression assessed at age 18 years." (PMID 30414442, 2019). "In this study, a linear regression model revealed that telomere length decreased as CRP levels increased in men, regardless of the depression status, and in women with major depression or depressed affect, but not in women without depression." (PMID 31109116, 2019). "A significant elevation of serum IL-6 levels was observed in patients with major depression, but the change in serum CRP levels was not significantly different between the groups." (PMID 30899619, 2019). "A recent cumulative meta-analysis confirmed the robust nature of the depression–inflammation relationship, showing evidence of increased circulating interleukin-6 and C-reactive protein (CRP) in depressed compared with non-depressed individuals." (PMID 30220259, 2019). "In addition, the clinical evidence suggests increased pro-inflammatory markers in patients with depression (increased TNF-α, CRP, and IL-6)." (PMID 31258489, 2019). "Among men without depression, those with an elevated CRP level had increased odds of having a shortened telomere length compared to men with low CRP levels after controlling for covariates (adjusted odds ratio 1.77, 95% confidence interval (CI) 1.09–2.90)." (PMID 31109116, 2019). "Among men without depression, those with an elevated CRP level had increased odds of having a shortened telomere length compared to men with low CRP levels after controlling for covariates." (PMID 31109116, 2019). "A significant and decreasing linear trend in telomere length was found as CRP levels increased in men, regardless of the depression status, and women with major depression or depressed affect (p values < 0.05)." (PMID 31109116, 2019). "Also, reduced hippocampal volume and increased inflammatory cytokine levels, including IL-6 and C-reactive protein (CRP), were observed in patients with major depressive disorder." (PMID 31581672, 2019). "Meanwhile, the prevalence of depression in women was not significantly different between the groups of high and low hs-CRP levels (9.79% vs. 7.34%, P = 0.215)." (PMID 30760746, 2019).